VDAC1 (voltage dependent anion channel 1)
Diseases named in the same sentence as VDAC1 in open-access papers (continued):
Sharing a sentence is not in itself a finding about the gene and the disease.
Sepsis (7 papers, 2011 to 2025). Sepsis is defined as life-threatening organ dysfunction caused by a dysregulated host response to infection. "We observed a close association between the loss of VDAC1 and the loss of mitochondrial membrane ΔΨm in the septic ARVMs, implying that 5HD provided protection against sepsis-induced OMM damage." (PMID 21712982, 2011). "Therefore, we concluded that (+)3C‐20 targeting VDAC1 in PBMCs from sepsis‐associated ALI patients, inhibiting mtDNA release to reduce inflammation, promises to be a potential application of ALI in future clinical research." (PMID 39556713, 2024). "Meanwhile, TMBIM6 overexpression has been shown to enhance the interaction with VDAC1, thereby protecting myocardial mitochondria and cardiac function against sepsis." (PMID 40694561, 2025). "Collectively, we discovered for the first time that fatty acid synthesis promoted mtDNA release-related EC dysfunction via ETS1-mediated VDAC1 ubiquitination and oligomerization, thereby leading to the lung injury in sepsis." (PMID 40369168, 2025). "In conclusion, VDAC1, HSPA8, SOD1, HSPA9, TXN, and SNCA have been identified as oxidative stress-related genes associated with sepsis-induced ALI." (PMID 40694561, 2025). "TMBIM6 can exert cardioprotective effects against LPS-induced sepsis by interacting with mitochondrial Ca2+ uptake, inhibiting/blocking overexpression of the VDAC1, and preventing its oligomerization." (PMID 39664568, 2024). "Sepsis produced a significant downregulation of VDAC1, and upregulation of Bax levels, along with mitochondrial membrane potential collapse in ARVMs." (PMID 21712982, 2011). "This suggests that VDAC1 may mitigate sepsis-induced organ damage by regulating mitochondrial dysfunction and oxidative stress." (PMID 40694561, 2025). "Our findings suggest that PGAM5-mediated mitophagy dysfunction may be a crucial factor leading to sepsis-induced microvascular injury, primarily interacting with VDAC1-mediated mitochondrial membrane dysfunction." (PMID 39664568, 2024). "The logistic regression algorithm identified 8 genes (VDAC1, HSPA8, SOD1, HSPA9, TXN, NDUFS3, HSP90AB1, SNCA), among which 6 genes were closely correlated with the onset of sepsis-induced ALI (p < 0.05)." (PMID 40694561, 2025). "The expression levels of VDAC1, HSPA8, SOD1, and HSPA9 were significantly decreased in the sepsis-induced ALI group compared to the control group (p < 0.0.5)." (PMID 40694561, 2025). "Based on our previous research, we further explored the role of mitophagy dysfunction mediated by VDAC1 and its upstream regulatory protein PGAM5 in sepsis-induced coronary microvascular injury." (PMID 39664568, 2024). "Analyses of immunoblot data revealed that sepsis produced decreased levels of ANT and its complex with both SUR2 and VDAC1." (PMID 21712982, 2011). "Finally, we analyzed the expression of VDAC1, HSPA8, SOD1, HSPA9, TXN, and SNCA in sepsis-induced ALI in the meta-GEO cohort." (PMID 40694561, 2025). "VDAC1 oligomerization promoted the release of mtDNA to induce EC dysfunction via activating cGAS-STING signaling pathway, thereby leading to lung injury during sepsis." (PMID 40369168, 2025). "Therefore, we next analyzed the expression of VDAC1, HSPA8 and HSPA9 in the blood samples of patients with sepsis-induced ALI at the clinical level." (PMID 40694561, 2025). "The proportion of neutrophils exhibited a significant negative correlation with the expression of VDAC1, HSPA8, SOD1, HSPA9 and TXN, and a significant positive correlation with SNCA expression in sepsis-induced ALI." (PMID 40694561, 2025).
viral infections (7 papers, 2005 to 2025). "Combining the protein functional analysis in the current study with previous reports, we also observed that MAPRE1 and VDAC1 were related to virus infection." (PMID 33329485, 2020). "Immunoprecipitation experiments with anti-PB1-F2 polyclonal serum revealed that the PB1-F2 protein interacts with ANT3 and VDAC1 during the viral infection." (PMID 16201016, 2005). "The observed VDAC phosphorylation events in viral infections may also regulate channel conformation and VDAC1 stability during infection, constituting an interface of host–pathogen competition over control of intrinsic cell death pathways." (PMID 37238738, 2023). "Although not functionally characterized during viral infection, VDAC1 Ser104 phosphorylation was observed in all three studies, a phosphorylated residue previously shown to stabilize VDAC1 and induce apoptosis." (PMID 37238738, 2023). "Furthermore, to determine whether PB1-F2 interacts with ANT3 and VDAC1 within the context of viral infection, we infected Flag-ANT3- and Flag-VDAC1-transfected 293T cells with either a wild-type PR8 virus or with its correspondent virus knocked out for PB1-F2 protein expression." (PMID 16201016, 2005).
colon carcinoma (6 papers, 2019 to 2024). "Similarly, colon cancer cells showed the highest increase of VDAC1 expression when CaEP was used (almost 100% of stained cells)." (PMID 32111987, 2020). "The specificity of the siRNA against human VDAC1 was demonstrated previously for human HCT-116 and murine CT26 colon carcinoma cells." (PMID 34200480, 2021). "Unlike VDAC1 removal, loss of VDAC2 or replacing its membrane-facing glutamate with glutamine renders human colon cancer cells largely resistant to ceramide-induced apoptosis." (PMID 31015432, 2019).
Hepatic steatosis (6 papers, 2018 to 2022). Steatosis is a term used to denote lipid accumulation within hepatocytes. "The specific mechanism might be related to the inhibition of mitochondrial respiratory chain complex I via suppressing the expression of VDAC1 so as to prevent “ energy surplus” by SA, which ultimately decreased the liver weight and improved hepatic steatosis." (PMID 34764866, 2021). "Coincidentally, sennoside A, which are the main components of sennosides, was reported to protect mitochondrial function and structure to improve hepatic steatosis by inhibiting the mitochondrial respiratory chain complex I and the voltage-dependent anion channel 1 (VDAC1)." (PMID 30336596, 2018). "Our research suggested that SA (30 mg/kg) protected the liver mitochondrial structure and function by targeting the mitochondrial/VDAC1 Pathway, suggesting that VDAC1 inhibition might contribute to SA-mediated mitochondrial protection in mice with HFD-induced hepatic steatosis." (PMID 34764866, 2021). "The authors suggest that VDAC1 inhibition may be an underlying mechanism of drugs, such as sennoside A, a commonly used clinical laxative stimulant, for protecting mitochondria in HFD-induced hepatic steatosis in mice." (PMID 30974751, 2019).
ischemia (6 papers, 2010 to 2025). A hypoperfusion of the BLOOD through an organ or tissue caused by a PATHOLOGIC CONSTRICTION or obstruction of its BLOOD VESSELS, or an absence of BLOOD CIRCULATION. "Thus, we assessed the effect of VDAC1 deficiency on collagen accumulation in the renal interstitium after ischemia using picro-sirius red staining." (PMID 32290153, 2020). "The return of protein levels of VDAC1 after ischemia is accompanied by recovery of mitochondrial dynamics and functions, morphological regeneration of the kidney, and the return of normal kidney functions." (PMID 32290153, 2020). "Deletion of VDAC1 exacerbated ischemia-induced mitochondrial fission, but did not aggravate morphological damage to proximal tubules after ischemia." (PMID 32290153, 2020). "We aimed to determine if VDAC1 plays a role in recovery of mitochondrial and kidney functions after ischemia-induced acute kidney injury (AKI)." (PMID 32290153, 2020). "LC3B (red) that colocalized with VDAC1 (green) in the cytoplasm showed that increased mitophagy (yellow) occurred in cortical neurons, suggesting that ischemia and reperfusion significantly promoted mitophagy (p < 0.05)." (PMID 30018669, 2018). "We also conclude that VDAC1 plays an important role in morphological regeneration of the proximal tubule segment of the nephron and the absence of this channel hinders recovery of the proximal tubules and impedes the return of kidney functions after ischemia." (PMID 32290153, 2020). "Finally, these data show that VDAC1 is indispensable for efficient recovery of ADP-stimulated mitochondrial respiration following ischemia." (PMID 32290153, 2020). "Because VDAC1 is required for functional mitochondria and neuronal survival, targeting miR-7 after ischemia may increase VDAC1 expression and subsequently confer neuroprotection." (PMID 30305621, 2018). "Not only is VDAC1 important for maintaining mitochondrial energy metabolism and dynamics in non-injured kidney, but it plays a major role in the full recovery of these functions, restoration of kidney morphology and functions, and survival after ischemia-induced AKI." (PMID 32290153, 2020). "However, deletion of VDAC1 blocks recovery of activities of these complexes following ischemia." (PMID 32290153, 2020). "Hence, we tested whether the absence of VDAC1 stimulates mitochondrial fission in non-injured and ischemia-injured mitochondria using the association of DRP1 with the mitochondria as a marker." (PMID 32290153, 2020). "Remarkable decreases in all three VDAC isoforms, especially VDAC1 and VDAC3, were observed in rat vulnerable hippocampal CA1 subfield after 15 min of global ischemia followed by reperfusion (I/R)." (PMID 30305621, 2018). "The lack of VDAC1 is sufficient to induce association of DRP1 with mitochondria in the absence of ischemic injury and promotes mitochondrial fission whereas ischemia augments this increase." (PMID 32290153, 2020). "All three VDAC isoforms, especially VDAC1 and VDAC3, were downregulated in the susceptible hippocampal CA1 subfield, whereas no alteration occurred in ischemia-tolerant CA3/DG subfields, nor in postconditioning-treated brains." (PMID 30305621, 2018). "Furthermore, our data show that the lack of VDAC1 does not exacerbate ischemia-induced decreases in ATP, but blocks recovery of cellular ATP content after injury." (PMID 32290153, 2020). "In contrast, the functions of complexes II and IV were unaffected by ischemia and lack of VDAC1." (PMID 32290153, 2020). "The disruption of mitochondrial dynamics in VDAC1-deficient kidneys was accompanied by the lack of recovery of state 3 respiration, activities of complex I, complex III, and F0F1-ATPase, and ATP levels after ischemia." (PMID 32290153, 2020). "On day 7 after ischemia, VDAC1 levels were not different from sham controls." (PMID 32290153, 2020).
ischemia (continued). "However, the absence of VDAC1 in injured kidneys hinders recovery of mitochondrial functions and dynamics, impedes regeneration of renal morphology and return of kidney functions, and increases deposition of collagen in renal interstitium after ischemia." (PMID 32290153, 2020). "Moreover, the absence of VDAC1 blocks recovery of activities of complexes I and III after ischemia without reducing their protein levels." (PMID 32290153, 2020). "However, a substantial pool of these proteins was not functional after ischemia, which suggested that the subunits of complexes I and III were present, but their assembly was disrupted and could not be repaired in the absence of VDAC1." (PMID 32290153, 2020).
acute lymphoblastic leukemia (5 papers, 2012 to 2021). Leukemia with an acute onset, characterized by the presence of lymphoblasts in the bone marrow and the peripheral blood. "In another case, transcript analysis from dexamethasone resistant childhood acute lymphoblastic leukemia (ALL) patients revealed a significantly lower expression of VDAC1 with respect to control samples." (PMID 31159324, 2019). "Up-regulation of VDAC1 expression was noted in acute lymphoblastic leukemia (ALL) cell lines following prednisolone treatment." (PMID 30542671, 2017). "Another study highlighted that dexamethasone-resistant childhood acute lymphoblastic leukemia (ALL) patients showed lower expression levels of VDAC1 than healthy controls; hence, VDAC1 might be considered a predictor of the chemotherapy response for childhood ALL." (PMID 33946271, 2021). "Up-regulation of VDAC1 expression was observed in three different acute lymphoblastic leukemia (ALL) cell lines (697, Sup-B15, and RS4;11) following prednisolone treatment, an observation that can be explored for predicting eventual outcome in childhood ALL." (PMID 23233904, 2012).
breast invasive carcinoma (5 papers, 2021 to 2023). "Results from the survival analysis showed that the up-regulated genes AKT3 and VDAC1 and the down-regulated genes ADCYAP1R1, GFAP, and C4A were found to be significantly associated with the overall survival of the patients with breast invasive carcinoma." (PMID 37834358, 2023). "We found that the FTD DEGs, AKT3, UBE2N, VDAC1, ADCYAP1R1, C4A, and GFAP showed significant comorbidity in breast invasive carcinoma patients at a p-value < 0.05." (PMID 37834358, 2023).
diabetic nephropathy (5 papers, 2020 to 2024). "Meanwhile, studies have reported that VDAC1 is also involved in the development of diabetic nephropathy." (PMID 38989148, 2024). "The presence of some proteins (i.e., histone-lysine N-methyltransferase (MLL3), α-microglobulin/bikunin precursor (AMBP), and voltage-dependent anion-selective channel protein 1 (VDAC1)) in uEVs were observed in samples from diabetic nephropathy patients." (PMID 34822562, 2021). "It has been shown that diabetic nephropathy is accompanied by diminished levels of VDAC1 in the kidney; however, the role of individual VDAC isoforms in diabetic nephropathy or in mitochondrial dysfunction associated with acute kidney injury have not been assessed." (PMID 32290153, 2020).
Insulin resistance (5 papers, 2021 to 2025). Increased resistance towards insulin, that is, diminished effectiveness of insulin in reducing blood glucose levels. "Increased glucose transport and improved insulin resistance were found in CY-09-treated 3×Tg-AD mice; we also detected the expressions and distribution of HK, which is the first enzyme that phosphorylates glucose when associated with VDAC1 in the mitochondria." (PMID 36978970, 2023). "This was demonstrated by using sulforaphane for treating insulin resistance, with insulin resistance being improved along with a reduced MAM disruption and impaired interaction between VDAC1 and IP3R1." (PMID 33917091, 2021).
acute kidney injury (4 papers, 2020 to 2026). Sudden and sustained deterioration of the kidney function characterized by decreased glomerular filtration rate, increased serum creatinine or oliguria. "Lastly, our results suggest that VDAC1 reduces progression of renal fibrosis after acute kidney injury." (PMID 32290153, 2020). "In the absence of TRIM65, VDAC1 is maintained at a lower level of protein through the autophagy pathway, which promotes the repair of mitochondrial function and ultimately protects against acute kidney injury." (PMID 40264575, 2025).
bladder cancer (4 papers, 2022 to 2026). "Overall, the results of this study using BC cell lines and mouse models point to si-VDAC1 as a potential treatment for bladder cancer." (PMID 38607066, 2024). "Bladder cancer tissues from human patients show high expression levels of VDAC1 as compared to healthy tissues." (PMID 38607066, 2024).
cardiomyopathies (4 papers, 2020 to 2025). "Remarkably, in both cardiomyopathies, Ca2+ storage in the mitochondrion was diminished by downregulation of one of the involved genes (Vdac1 in CCC and Slc25a5 in IHF mice)." (PMID 41296444, 2025). "This HFHSD-induced cardiomyopathy is characterized by a reduced mitochondrial Ca2+ uptake secondary to a reduced formation of the IP3R1/Grp75/VDAC1 Ca2+ channeling complex in MAM but without any alteration of the mitochondrial Ca2+ uniporter." (PMID 33258101, 2020).
cognitive deficits (4 papers, 2019 to 2025). "Dysregulation of Vdac1 and its PTMs are implicated in impaired energy metabolism, oxidative stress, and neurodegenerative processes associated with cognitive impairment." (PMID 38455734, 2024). "Oxidative damage in the brains of neurodegenerative patients caused by nitration and carbonylation of Vdac1 may impair channel function, promote the pathogenesis and progression of brain disease, and contribute to cognitive impairment." (PMID 38455734, 2024). "Furthermore, autopsy tissue sections showed concordantly dysregulated miR-320a and voltage-dependent anion channel 1 levels in HIV-1 patients suffering from mild cognitive impairment." (PMID 31323913, 2019).
colitis (4 papers, 2022 to 2025). Inflammation of the colon. "Recent studies have also demonstrated that knocking out several genes encoding crucial mitochondrial proteins, such as voltage-dependent anion channel 1 (VDAC1) and prohibitin 1 (PHB1), can disrupt mitochondrial function and aggravate experimental colitis in mice." (PMID 40089459, 2025). "Recent studies from our group using animal models of inflammatory diseases such as arthritis and colitis have demonstrated that depleting or inhibiting VDAC1 reduced inflammation and alleviated other symptoms, suggesting its role in modulating inflammatory processes." (PMID 39456237, 2024).
epilepsy (4 papers, 2020 to 2025). A brain disorder characterized by episodes of abnormally increased neuronal discharge resulting in transient episodes of sensory or motor neurological dysfunction, or psychic dysfunction. "Cell apoptosis was detected in epilepsy neurons, refractory epilepsy neurons with the gain function of VDAC1, and refractory epilepsy neurons with the loss function of VDAC1 using TUNEL labeling." (PMID 33336032, 2020). "MAMs‐related proteins (e.g., VAPB and VDAC1) may serve as early diagnostic biomarkers for epilepsy." (PMID 41456957, 2025). "Though there are some studies concerning the connection between apoptosis and epilepsy, little is known about the role of VDAC1 in epilepsy as well as in refractory epilepsy." (PMID 33336032, 2020). "Accompanied by the release of cytochrome C into cytosol, caspase 9 increased obviously in refractory epilepsy neurons with the gain function of VDAC1 (117.6 ± 1.75%, P < 0.05) and decreased in refractory epilepsy neurons with the loss function of VDAC1 (84.7 ± 2.66%, P < 0.05)." (PMID 33336032, 2020). "In this part, we could see that Bcl-2 inhibited the cell apoptosis, release of cytochrome C, and activation of caspase 9 in epilepsy, which could be strengthened by VDAC1 downregulation." (PMID 33336032, 2020). "Apart from that in refractory epilepsy, we also detected the role of VDAC1 in epilepsy." (PMID 33336032, 2020). "VDAC1 regulated the pro-apoptotic effects of Bax and Bcl-2 in epilepsy." (PMID 33336032, 2020). "Therefore, Bax induced the cell apoptosis, release of cytochrome C, and increase of caspase 9 in epilepsy, which could be inhibited by VDAC1 downregulation." (PMID 33336032, 2020). "Also, VDAC1 increase and VDAC2 decrease have been documented in epilepsy-related mitochondrial dysfunction." (PMID 36350974, 2022).
Huntington disease (4 papers, 2007 to 2025). Huntington disease (HD) is a rare neurodegenerative disorder of the central nervous system characterized by unwanted choreatic movements, behavioral and psychiatric disturbances and dementia. "The predicted Sp1 site in the Vdac1 gene was of special interest since aberrant Sp1 mediated interaction has earlier been implicated in Huntington's disease mechanism." (PMID 18000542, 2007).